DYRK1A (dual specificity tyrosine phosphorylation regulated kinase 1A)
Diseases named in the same sentence as DYRK1A in open-access papers (continued):
Sharing a sentence is not in itself a finding about the gene and the disease.
Down syndrome (continued). "Due to its location, triplication of the DYRK1A locus in Down syndrome (DS) results in a 1.5-fold increase of DYRK1A mRNA and protein levels in the fetal and adult brain." (PMID 34445804, 2021). "It would also explain some of the altered morphology in Down syndrome (with increased DYRK1A gene dosage) characterised by thicker retinas and altered visuo-cortical processing as observed by visual evoked potential (VEP) testing." (PMID 33562844, 2021). "Here, we uncovered that dual‐specificity tyrosine phosphorylation regulated kinase 1A (DYRK1A), a kinase critical in Down's syndrome pathogenesis, directly bound to and phosphorylated MEF2D at Ser251 in vitro." (PMID 34109727, 2021). "Overexpression of DYRK1A produces similar neurodevelopmental and neurodegenerative changes to animal disease models with Down syndrome." (PMID 33562844, 2021). "Studies using partially trisomic Down syndrome mouse models or transgenic mice that overexpress Dyrk1a indicate that GTE-EGCG ameliorates some cognitive 26, skull 18 and skeletal alterations 6,7." (PMID 33633179, 2021). "The human DYRK1A gene is located in the Down syndrome critical region and its levels are important in the pathogenic mechanism." (PMID 32081899, 2020). "Epigallocatechin gallate (EGCG) is an inhibitor of DYRK1A, a serine/threonine kinase considered to be a major contributor of cognitive dysfunctions in Down syndrome (DS)." (PMID 32092951, 2020). "EGCG was initially identified as a candidate therapeutic treatment for Down syndrome (DS) phenotypes based largely on the in vitro demonstration that EGCG inhibits Dual-specificity tyrosine-phosphorylation regulated kinase 1A (DYRK1A) activity." (PMID 32591597, 2020). "DYRK1A is also located within the critical region for Down syndrome; therefore, understanding the role of DYRK1A in brain development is crucial for understanding the pathobiology of multiple developmental disorders." (PMID 32467234, 2020). "Located within the Down syndrome (DS) critical region on chromosome 21q22.13, DYRK1A has been studied extensively in animals to elucidate its role in Down syndrome." (PMID 33159716, 2020). "Epigallocatechin-3-gallate (EGCG) is a candidate therapeutic for Down syndrome (DS) phenotypes based on in vitro inhibition of DYRK1A, a triplicated gene product of Trisomy 21 (Ts21)." (PMID 32591597, 2020). "Abnormal expression and activity of DYRK1A contribute to numerous human malignancies, Down syndrome, and Alzheimer’s disease." (PMID 32957634, 2020). "DYRK1A is overexpressed in Down Syndrome, and DYRK1A overexpression in mice led to perturbations of the methionine cycle, specifically a decrease in plasma homocysteine level." (PMID 30862944, 2019). "The DYRK1A gene is located on chromosome 21 (21q22.2), a region known as the Down- Syndrome Critical Region (DSCR)." (PMID 30885273, 2019). "DYRK1A inhibitor as a therapeutic agent for Down syndrome has been widely studied and developed and has been tested in clinical trials." (PMID 30760866, 2019). "Dual-specificity tyrosine phosphorylation-regulated kinase 1A (DYRK1A) is a Ser/Thr protein kinase located in the Down syndrome critical region at chromosome 21." (PMID 31723029, 2019). "Dual-specificity tyrosine-phosphorylation regulated kinase 1A (DYRK1A) is encoded in chromosome 21, which is a critical region associated with Down's syndrome." (PMID 31105874, 2019). "Down Syndrome (DS), the most common cause of genetic intellectual disability, is characterized by over-expression of the APP and DYRK1A genes, located on the triplicated chromosome 21." (PMID 30389461, 2019). "Dyrk1A, also found in the Down syndrome critical region of chromosome 21, is involved in Wnt signaling as well." (PMID 29587359, 2018). "DYRK1A maps to the Down syndrome (DS) critical genetic region and is thought to contribute to the manifestations of DS." (PMID 30383316, 2018).
Down syndrome (continued). "Growing evidence supports the implication of DYRK1A in the development of cognitive deficits seen in Down syndrome (DS) and Alzheimer's disease (AD)." (PMID 30115750, 2018). "Overexpression of the Dual-specificity Tyrosine Phosphorylation-Regulated Kinase 1A (DYRK1A) gene contributes to the retardation, craniofacial anomalies, cognitive impairment, and learning and memory deficits associated with Down Syndrome (DS)." (PMID 30496304, 2018). "Dual-specificity tyrosine phosphorylation-regulated kinase 1A (DYRK1A) is a potential drug target because of its role in the development of Down syndrome and Alzheimer’s disease." (PMID 29364148, 2018). "In humans, the DYRK1A gene is located on chromosome 21 (21q22.13), which is part of the so-called Down-Syndrome Critical Region (DSCR)." (PMID 29615569, 2017). "The DYRK1a gene is located in the Down syndrome critical region on chromosome 21, which results in a 1.5‐fold increase of Dyrk1a protein levels." (PMID 28779511, 2017). "DYRK1A lies within the Down syndrome critical region on chromosome 21, and an excessive gene dosage of DYRK1A is thought to account for some of the central nervous system phenotypes of this disorder." (PMID 28884684, 2017). "Most evidence for developmental cross-talk between DYRKs and Hh stems from studies on DYRK1A, neuronal development, and the Down syndrome." (PMID 29615569, 2017). "DYRK1A, localized in the Down syndrome critical region of chromosome 21, is considered to be a strong candidate gene for intellectual disability related to DS." (PMID 28775333, 2017). "In humans, DYRK1A is located on chromosome 21q22.13 in the “Down Syndrome Critical Region (DSCR)” at 21q22.1–q22.3." (PMID 29021890, 2017). "Dual-specificity tyrosine–phosphorylation regulated kinase 1A (DYRK1A) is localized in the Down syndrome critical region of chromosome 21." (PMID 28775333, 2017). "Increased DYRK1A gene dosage, such as occurs in Down syndrome, is known to affect neural progenitor cell differentiation, while haploinsufficiency of DYRK1A is associated with severe microcephaly." (PMID 28884684, 2017). "Intellectual disability accompanied by microcephaly was recapitulated in a murine model by overexpressing Dyrk1a which mimicked Down syndrome phenotypes." (PMID 29021890, 2017). "The defects of gonads and germ cells in Down Syndrome patients suggest that overexpression of DYRK1A has potential function on primordial germ cells (PGCs) development." (PMID 29127398, 2017). "Dyrk1A overexpression also leads to increase of 3R-tau expression and cognitive deficits in Ts65Dn Down syndrome mice." (PMID 28775333, 2017). "Down syndrome shows severe defect of gonads and germ cells, however, the distinct function of increased DYRK1A dosage in PGCs remains obscured." (PMID 29127398, 2017). "The defects of gonads and germ cells in Down Syndrome suggest that overexpression of DYRK1A has potential effect on primordial germ cells (PGCs) development." (PMID 29127398, 2017). "Editors' choice:In vivo validation of a potent DYRK1A inhibitor, with proven clinical safety, using Down-syndrome- and Alzheimer's-disease-like models." (PMID 27483355, 2016). "The dual-specificity tyrosine phosphorylation-regulated kinase 1A (DYRK1A) (MIM 600855) is located in the Down syndrome critical region of chromosome 21." (PMID 26922654, 2016). "The significance of DYRK1A has been recently highlighted by the discovery of its contribution to Down syndrome (DS) pathogenesis." (PMID 27483355, 2016). "Dyrk1a maps to the Down Syndrome (DS) critical region of human chromosome 21 and overexpression of Dyrk1a is a major contributor to the neurodevelopmental defects present in DS patients." (PMID 27880803, 2016). "DYRK1A, located on the Down syndrome (DS) critical region of chromosome 21, was found to be overexpressed in brains of DS and Alzheimer's disease individuals." (PMID 27807027, 2016).
Down syndrome (continued). "DYRK1A was first described as a cadidate gene for intellectual disability in Down syndrome because of its location on the “Down syndrome critical region” of chromosome 21." (PMID 27909399, 2016). "For example, the NFATc circuit is cooperatively destabilized by a 1.5-fold increase in the DSCR1 and DYRK1A genes, which reduce NFATc activity leading to characteristics of Down’s syndrome." (PMID 26030820, 2015). "The DYRK1A protein function is very sensitive to gene dosage and since Down syndrome patients have a higher DYRK1A expression due to the three DYRK1A copies in their genome, DYRK1A is considered constitutively overactive in their cells." (PMID 26310823, 2015). "DYRK1A levels are known to be increased in Down syndrome patients and it has been shown to phosphorylate SEPT4 at S68 and S107." (PMID 25888325, 2015). "Specifically, DYRK1A overexpression, as observed in Down syndrome, affects pathways involved in synaptogenesis and synaptic plasticity, and moves the excitation/inhibition balance toward inhibition." (PMID 26136701, 2015). "Down syndrome is characterized by trisomy of chromosome 21; specifically, the resulting increase in DYRK1A copy number and activity is thought to be a key driver of pathology." (PMID 25998054, 2015). "An illustrative example of the role of over-expression of a particular protein in the pathogenesis of a given neurodegenerative disease is given by the dual-specificity tyrosine phosphorylation-regulated kinase 1A (DYRK1A) in Down syndrome." (PMID 25988147, 2014). "The DYRK1A gene lies within the critical region on chromosome 21 and is duplicated and overexpressed in Down Syndrome (DS)." (PMID 24429107, 2014). "In Down Syndrome, DYRK1A overexpression is due to the extra copy of chromosome 21(or part of chromosome 21), which is known as gene dosage effect." (PMID 24901999, 2014). "In fact, DYRK1A over-expression deregulate multiple pathways in the developing and aging Down syndrome brain, affecting hundreds of proteins, including cytosolic, cytoskeletal, and nuclear proteins, transcription factors." (PMID 25988147, 2014). "The human DYRK1A gene is located on chromosome 21 and its overexpression is considered to be related to Down syndrome phenotypes." (PMID 23825664, 2013). "We show here that the overexpression of the Down syndrome-related genes Dyrk1A and Rcan1 reduce the effect of NGF on NFAT promoter activity and the upregulation of PAI-1 in PC12 cells." (PMID 23825664, 2013). "In order to study the contribution of DYRK1A to Down syndrome phenotypes, we used a transgenic mouse model for Dyrk1A (TgDyrk1A)." (PMID 23342120, 2013). "The best-studied member of the DYRK family is DYRK1A, owing to its role in the pathology of Down syndrome and the early onset of neurodegeneration." (PMID 23665168, 2013). "Transgenic mice that carry an extra copy of the Dyrk1A gene exhibit neurodevelopmental delay, motor abnormalities and cognitive deficits that resemble those described in Down syndrome individuals." (PMID 23825664, 2013). "More specifically, DYRK1A is considered to be a strong candidate gene for mental retardation and is localized in the Down syndrome critical region of chromosome 21." (PMID 23077488, 2012). "In humans, DYRK1A, the best-characterized mammalian DYRK, is implicated in learning defects and is mapped to the “Down syndrome critical region” of chromosome 21 with septin 4 as its specific target." (PMID 22174761, 2011). "The dual-specificity tyrosine phosphorylation regulated kinase 1A (DYRK1A) gene is located within the Down syndrome critical region on chromosome 21." (PMID 21573099, 2011). "These individuals carry a small duplication of 10 genes including DYRK1A, consistent with a role for DYRK1A as a candidate gene in Down syndrome." (PMID 19242551, 2009). "DYRK1A has attracted considerable interest as a "candidate gene" potentially responsible for several traits related to Down syndrome." (PMID 18366763, 2008).
Down syndrome (continued). "The proposed role of DYRK1A in Down syndrome-related mental retardation was supported by analyses of genetically altered mice." (PMID 18366763, 2008). "Overexpression of the human DYRK1A gene due to the presence of a third gene copy in trisomy 21 is thought to play a role in the pathogenesis of Down syndrome." (PMID 18366763, 2008). "Expression of the human DYRK1A was shown to be increased 1.5-fold in fetal and adult brains from subjects with Down syndrome." (PMID 18366763, 2008). "Dysregulated expression and activity of DYRK1A, dual specificity tyrosine phosphorylation regulated kinase 1A, is a feature of several neurodevelopmental and neurodegenerative diseases, including Down syndrome, DYRK1A syndrome, autism spectrum disorders, Alzheimer's disease, and Parkinson's disease." (PMID 41676546, 2026). "Because DYRK1A dysregulation contributes to developmental disorders such as Down syndrome as well as tumorigenesis, future strategies aiming at regulating FAM53C activity may benefit a broad range of patients." (PMID 42059432, 2026). "Longitudinal studies in individuals with Down syndrome could also assess whether modulating DYRK1A expression confers broader health benefits, such as improvements in cognitive function, cardiac health or immune regulation." (PMID 39840732, 2025). "Interestingly, an increased dosage of DYRK1A, located on chromosome 21, is thought to participate in the cognitive manifestations of Down syndrome, suggesting that a correct balance of DYRK1A dosage is essential for brain development and cognitive function." (PMID 40182141, 2025). "Due to trisomy 21, DYRK1A is overexpressed in individuals with Down syndrome (DS)." (PMID 41189746, 2025). "Similarly, NMDA-dependent LTP can be rescued either by the copy number restauration of Dyrk1a levels or Brwd1 in the Ts65Dn mouse model of Down syndrome." (PMID 40003558, 2025). "In conclusion, DYRK1A is emerging as multifunctional critical modulator of viral infection, and therefore an attractive therapeutic target for the management of specific viral infections in people with Down syndrome and beyond." (PMID 40519271, 2025). "Furthermore, the MoS2/WTe2 FET biosensor was used as a sensing platform to detect the Down syndrome-related DYRK1A gene, achieving a detection limit of 10 aM and high specificity." (PMID 38276744, 2024). "Therefore, downregulating DYRK1A has been explored as a potential therapeutic strategy for Down syndrome, with promising results observed from in vivo mouse models and human clinical trials that administered epigallocatechin gallate." (PMID 39114642, 2024). "DYRK1A is located in human chromosome 21q22.2, known as the Down syndrome critical region (DSCR)." (PMID 39109359, 2024). "EE was shown to mitigate symptoms and improve social and cognitive outcomes in models of autism and research on genetic factors, such as Dyrk1a in Down syndrome models, provided insights into the gene-by-environment interactions that influence neurodevelopment and behavior." (PMID 39697184, 2024). "DYRK1A targeted ASOs could be a viable therapeutic approach to improve the quality of life for individuals with Down syndrome and their families." (PMID 39114642, 2024). "The proposed asymmetric Schottky barrier-generated MoS2/WTe2 FET biosensor achieved a 105 rectified signal, sufficient reliability and stability (maintained for 60 days), ultra-sensitive detection (10 aM) of the Down syndrome-related DYRK1A gene, and excellent specificity in base recognition." (PMID 38276744, 2024). "Consequently, an overexpression of DYRK1A has been reported to result in cognitive impairment, a key phenotype of individuals with Down syndrome." (PMID 39114642, 2024). "DYRK1A, is located within the Down syndrome critical region (DSCR)." (PMID 39436397, 2024).
Down syndrome (continued). "Dyrk1a plays a key role in neuroproliferation and neurogenesis in the developing brain, and its gene is located on chromosome 21 (21q22.2), a region known as the Down syndrome critical region (DSCR)." (PMID 37469393, 2023). "Our study found ATP5O, DYRK1A, MRAP and OLIG2 have high burden in AVSD, especially DYRK1A that is highly and dynamically expressed in the developing heart, and the gain of function rather loss of function of it will leads to AVSD and Down’s syndrome phenotype." (PMID 36816019, 2023). "DYRK1A is located on chromosome 21, suggesting this gene may be overexpressed in cells from individuals with Down syndrome (DS)." (PMID 37015911, 2023). "The DYRK1A gene is located on human chromosome 21q22.2, covering the Down syndrome critical region." (PMID 36918100, 2023). "Dysregulation of DYRK1A occurs in neurodegenerative diseases, Down syndrome, cancers, and diabetes." (PMID 36918100, 2023). "This may be one of the reasons why a mere 1.5-fold overexpression of DYRK1A can induce drastic changes in gene expression and pathophysiological consequences in Down syndrome patients." (PMID 37802655, 2023). "DYRK1A is one of the most important candidate genes to explain Down syndrome (DS) neuropathology." (PMID 36590914, 2022). "DYRK1A overexpression may contribute to the synaptic dysfunction and cognitive decline in AD and Down syndrome patients." (PMID 36081896, 2022). "Moreover, DYRK1A is localized in the Down syndrome critical region of chromosome 21 and is considered a strong candidate for learning defects associated with Down syndrome." (PMID 34257281, 2021). "EGCG may normalize DYRK1A (involved in neural plasticity) overproduction in Down syndrome, improving behavioral and neural phenotypes." (PMID 34209677, 2021). "DYRK1A plays a key role in the neural proliferation and neurogenesis of the developing brain, and its gene is located on chromosome 21 (21q22.2), which is a region known as the Down syndrome critical region (DSCR)." (PMID 34445804, 2021). "Our findings reveal an unexpected link of mitochondrial protein biogenesis and DYRK1A signaling and can enable an understanding of the pathophysiological consequences of dysfunctional DYRK1A in DYRK1A-related syndrome, Autism Spectrum Disorder, and Down syndrome." (PMID 34257281, 2021). "According to recent literature, DYRK1A appears to be involved in various diseases, including Alzheimer’s disease (AD), Down syndrome (DS), and cancer, and many efforts have evolved over the last five years toward the identification of potent and selective DYRK1A inhibitors." (PMID 34832868, 2021). "Since humans with Down syndrome have three copies of DYRK1A, and since autopsy data indicate that DYRK1A protein is expressed at 50% higher levels than in normal, one of the early goals of DYRK1A inhibitor research was developing their use in early childhood for people with Down syndrome." (PMID 34335466, 2021). "DYRK1A regulates the interaction between WDR68 and Huntington-associated protein 1 (Hap1), which may contribute to postnatal growth retardation in Down syndrome (DS)." (PMID 34205123, 2021). "Although it is currently under study, the inhibition of DYRK1A could improve the cognitive performance in pathologies associated to the loss of neuronal functions and plasticity, e.g., FASD, Autism, or Down Syndrome." (PMID 32760684, 2020). "DYRK1A contributes to cognitive disability in Down syndrome." (PMID 32341405, 2020). "DYRK1A (dual-specificity tyrosine phosphorylation-related kinase 1A) is a dual-specificity protein kinase which gene is located on 21q22.2 of human chromosome 21 overexpressed in Down syndrome (DS)." (PMID 32092951, 2020). "DYRK1A is abnormally expressed in Down syndrome, Alzheimer′s disease, Pick′s disease, lung cancer, cervical cancer, gastrointestinal stromal tumors (GIST), glioblastoma, melanoma, acute megakaryoblastic leukemia, acute lymphoblastic leukemia, and acute myeloid leukemia." (PMID 32957634, 2020).